VDR (vitamin D receptor)
Diseases named in the same sentence as VDR in open-access papers (continued):
Sharing a sentence is not in itself a finding about the gene and the disease.
colitis (continued). "Hypoxia was protective against DSS-induced colitis, and VDR is instrumental in it." (PMID 35711312, 2022). "IL-10 knockout mice have lower intestinal VDR expression and develop spontaneous colitis." (PMID 36076980, 2022). "Moreover, VDR deletion in intestinal epithelial cells leads to defective autophagy in colitis, observed in inflammatory bowel disease." (PMID 36233580, 2022). "Animals kept on a vitamin D-depleted diet and mouse models specifically lacking vitamin D receptor (VDR) expression in the intestinal epithelium are more susceptible to experimental colitis, with different mechanisms of action of the vitamin." (PMID 35057450, 2022). "Indeed, the effects of vitamin D/VDR signaling in murine models indicate that following vitamin D administration the severity of chemically induced colitis is reduced and mucosal healing processes are more effective." (PMID 35057450, 2022). "However, few studies have focused on the effects of hypoxic treatment on barrier function during colitis, particularly the regulatory mechanism of VDR on the intestinal mucosal barrier under hypoxia." (PMID 35711312, 2022). "VDR also plays a protective role in colitis by regulating intestinal microbiota." (PMID 35600949, 2022). "Furthermore, VitD3 mediated VDR signaling reduced the severity of DSS colitis and found that it increased the ratio of M2 to M1 macrophages as well as inhibiting the differentiation of CD4+ T-cells into Th1 and Th17 T-helper cell subtypes." (PMID 36569849, 2022). "In another study, conditional intestinal vitamin D receptor (VDR) knockout led to an increased number of colon tumors in a murine colitis, which shifted the gut bacteria profile to be more susceptible to carcinogenesis, as well as increasing secondary bile acids." (PMID 35889090, 2022). "Consistently, VDR expression showed a decrease in the mucosal epithelial cells of colitis." (PMID 34380509, 2021). "As a result, overexpression of VDR in mice could maintain epithelial barrier function and attenuate colitis." (PMID 34579027, 2021). "Moreover, recent studies demonstrated that VDR functioning pathway is necessary for probiotics protection against colitis." (PMID 34899302, 2021). "Evidence from animal studies suggested that VDR knockout mice aggravated the symptoms of colitis." (PMID 34578802, 2021). "Mice lacking VDR activate the pro‐inflammatory NF‐κB pathway and are susceptible to Salmonella‐colitis and chemical‐induced colitis." (PMID 33559391, 2021). "This may provide another mechanistic explanation and useful therapeutic approach for prevention and treatment of colitis, either infectious or autoimmune, using these two nutrients occurring naturally in human diet and enhancing VDR expression." (PMID 34680413, 2021). "In this study, we have demonstrated that geniposide, as an anti-inflammatory compound partially inhibiting p-p38 MAPK, might alter the expression of VDR and weaken the effect of vitamin D supplements on alleviating colitis." (PMID 34650431, 2021). "In the present study, animal with colitis induced by DSS showed downregulated VDR expression." (PMID 34650431, 2021). "These demonstrated that VDR removal might be of some protective effect on oxazolone-induced Th2-mediated colitis." (PMID 32541827, 2020). "In an experimental colitis model, it was demonstrated that mice with the gut epithelium VDR deletion developed a more severe clinical colitis and worsened epithelial cell apoptosis, leading to an increased intestinal mucosa permeability, and promoted the Th1 and Th17 (T helper 17) mucosal response." (PMID 33396382, 2020). "In this study, oxazolone would be used to induce colitis in intestinal-specific VDR knockout mice." (PMID 32541827, 2020). "According to our findings, VDR plays a critical role in the action of vitamin D against colitis." (PMID 32422882, 2020).
colitis (continued). "Furthermore, it has been shown that the VDR, in conjunction with 1,25-(OH)2D3, protects against the onset of colitis in mice by maintaining barrier function within the gastrointestinal mucosal epithelium." (PMID 31286174, 2020). "VDR IEC specific KO mice also developed more severe DSS induced colitis compared to the wild type mice, implying that microbial dysbiosis may increase the susceptibility of colonic mucosa to DSS induced colitis." (PMID 30764829, 2019). "In this context, the probiotics can modulate the anti-inflammatory signaling pathway of the VDR in colitis with an unknown mechanism." (PMID 31231490, 2019). "An in vivo study demonstrated that vitamin D receptor null mice (VDR-/-) exhibit severe colitis." (PMID 31195621, 2019). "Moreover, the probiotic Lactobacillus rhamnosus strain GG and Lactobacillus plantarum trigger the expression and transcriptional activity of VDR and thereby protect from Salmonella-induced colitis in a VDR-dependent way." (PMID 30060580, 2018). "Moreover, the role of probiotics in regulating VDR signaling was assessed in vivo using a Salmonella typhimurium ATCC 14,028-induced colitis model in VDR knockout mice." (PMID 28555037, 2017). "It has been recently shown that a properly functioning VDR pathway is required for probiotic protection against colitis, a finding that is of importance since VDR expression can be significantly decreased in IBD patients as a consequence of chronic inflammation or dysbiosis." (PMID 29112157, 2017). "The severity of colitis was significantly higher in VDR and CYP27B1 knockout mice." (PMID 26130323, 2016). "Remarkably, the same authors demonstrated that the absence of intestinal epithelial VDR increased susceptibility to DSS-induced colitis, while decreasing butyrate-producing bacteria, Butyrivibrio." (PMID 28066436, 2016). "A previous work showed that vitamin D protects mice from dextran sodium sulfate-induced colitis through regulating the gut microbiome; and conversely dysbiosis as indicated by outgrowth of Proteobacteria was evident in the feces of the VDR KO mice under the toxin treatment." (PMID 27895587, 2016). "VDR KO CD8+ T cells induce colitis in the Rag KO recipients." (PMID 24502291, 2014). "Therefore it seems that autocrine IL-10 production by CD8+ T cells prevents overt colitis induced by VDR KO CD8+ T cells." (PMID 24502291, 2014). "In addition, co-transfer of VDR KO CD8+ T cells with naïve CD4+ T cells accelerated colitis development." (PMID 24502291, 2014). "Autocrine production of IL-10 limits VDR KO CD8+ T cell- induced colitis." (PMID 24502291, 2014). "Sorted 106 CD8/CD122+ T cell transfers from either WT or VDR KO mice did not induce weight loss or colitis in Rag KO recipients (data not shown)." (PMID 24502291, 2014). "In addition, co-transfer of VDR KO CD8+ T cells with naïve WT CD4+ cells accelerated the development of colitis in Rag KO recipients." (PMID 24502291, 2014). "VDR KO mice had normal FoxP3+ T regulatory cells that may have prevented the naïve CD8+ T cells from expanding and causing colitis." (PMID 24502291, 2014). "Vitamin D receptor (VDR) may play an important role in maintaining gastrointestinal mucosal integrity, as VDR-knockout mice have been shown to develop severe colitis." (PMID 24759961, 2013). "Therefore, we wanted to explore whether VDR-mediated NHE8 regulation was dependent on NF-κb p65 signaling pathway in colitis." (PMID 38004229, 2023). "We determined whether VDR mediates the effect of LCA on DSS-induced colitis." (PMID 36834927, 2023). "Furthermore, loss of VDR signaling in lymphocytes resulted in the generation of pathogenic CD8+ T cells and development of IBD and CD4+ T cells from VDR knock-out (KO) mice induced more severe colitis than wild-type CD4+ T cells." (PMID 36341397, 2022).
colitis (continued). "First, we used wild-type mice and VDR-KO mice to test the effect of hypoxia on the intestinal barrier function at the animal level with an aim to preliminarily explore the influence of hypoxia on colitis mice and their intestinal mucosal barrier as well as the role of VDR in it." (PMID 35711312, 2022). "Taken together, hypoxia may mediate the protective effect against acute mouse colitis through VDR." (PMID 35711312, 2022). "Therefore, VDR may act as a modulator of colitis by regulating autophagy and Paneth cells and further altering the gut community." (PMID 34579027, 2021). "Moreover, chemical-induced colitis in the VDR knockout mice was accompanied by high colonic expression of inflammation, including TNF-α, IL-1α, IL-1β and IL-8, leading to weight loss, ulceration and perforation of the bowel, endotoxemia and increased mortality." (PMID 34576700, 2021). "Interestingly, it has recently been shown that the microbiome modulates adaptive immunity in mice by formation of secondary BA species that act on RORγ+ regulatory T cells via the vitamin D receptor, thereby lowering the vulnerability for chemically induced colitis." (PMID 34604725, 2021). "Lack of 1,25(OH)2D3 or VDR deficiency results in microbial dysbiosis, leading to greater susceptibility to colitis, which might be important for patients with IBD8,47–49." (PMID 32355205, 2020). "Interestingly, epithelial-specific human VDR transgenic mice are protected from developing colitis due to the preservation of the mucosal barrier and protection of IECs from apoptosis through blocking TNF-α-induced p65 binding to the κB site of the PUMA gene promoter." (PMID 30804707, 2019). "VDR−/− mice are more prone than wild-type ones to develop intestinal dysbiosis- characterized by a depletion of Lactobacillus and butyrate-producing bacteria, and an increase in E. coli, Clostridium and Bacteroides- and severe colitis induced by dextran sodium sulfate (DSS)-mediated chemical insult." (PMID 29562608, 2018). "In addition, patients with polymorphisms of VDR were much more prone to IBD and the same trend was also presented in experimental animal colitis model, where Vdr knockout mice developed spontaneous colitis." (PMID 29675025, 2018). "The same probiotics in wild-type mice, indeed, were able to increase VDR expression and its transcriptional activity, with increased expression of antimicrobial peptides, and had the ability to confer physiological and histologic protection from Salmonella-induced colitis." (PMID 29112157, 2017). "Taken together, these results suggest that during the early phase of colitis, the probiotic and vitamin D combination may enhance systemic vitamin D metabolism to mitigate the need for local immune driven calcitriol production in colon and potentially activate existing VDR." (PMID 40944110, 2025). "LCA supplementation reduced intestinal inflammation in DSS−, TNBS−, and CD45RBhi T cell transfer models of colitis via TGR5 and VDR, as well as through the mitigation of epithelial cell apoptosis." (PMID 39767816, 2024). "A mixture of Lactobacillus rhamnosus dm905 and Lactococcus lactis mitigated colitis in Il10−/− mice, partly by decreasing PXR, TGR5, VDR, CAR, the NLRP3 inflammasome, and pro-inflammatory cytokines." (PMID 39767816, 2024). "HGT obstructed necroptosis in IEC by activating vitamin D receptor (VDR) signaling pathway, thereby attenuating DSS-induced colitis." (PMID 39840043, 2024). "To better understand the regulatory effect of VDR on NHE8 in colitis, we further examined the colonic NHE8 alterations in VDR−/−mice." (PMID 38004229, 2023). "The results showed that compared with the DSS group (DSS), the colitis in the DSS + DMOG group was relieved and the expression of VDR in the intestinal mucosal tended to increase after DMOG treatment." (PMID 35711312, 2022). "When VDRΔPC mice were co-housed with non-VDR-knockout mice, VDRΔPC mice exhibited resistance to DSS-induced colitis." (PMID 36014889, 2022).
colitis (continued). "Vitamin D receptor (VDR) expression in intestinal epithelial cells (IEC) decreases IEC apoptosis and thereby inhibits experimental colitis." (PMID 33810258, 2021). "A recently published study showed an indispensable role of VDR in maintaining colonic Treg cell homeostasis, which was critical to resistance to DSS-induced colitis." (PMID 34579027, 2021). "They then induced colitis-induced fibrosis by TNBS or DSS in mice with intestine-specific VDR deletion and they found that VDR deletion exacerbated intestinal fibrosis in both models." (PMID 34579023, 2021). "In addition, overexpression of VDR in colorectal epithelium could alleviate colitis." (PMID 34578802, 2021). "Administration of exogenous vitamin D or a VDR agonist in IBD mouse models has been shown to reduce TNF-α and suppress colitis." (PMID 32555936, 2020). "Intestinal epithelial VDR deletion leads to defective autophagy, through the regulation of ATG16L1 gene expression in experimentally-induced colitis." (PMID 29562608, 2018). "Another study indicated that vitamin D through vitamin D receptor (VDR) suppressed TNF-α-induced nuclear factor kappa B (NF-κB) activation and IL-6 up-regulation in epithelial cell isolated from transgenic mice and colitis animal model." (PMID 29456507, 2018). "VDR KO mice had increased numbers of naïve CD8+ T cells that when purified and then transferred to Rag KO recipients induced colitis as determined by histological staining." (PMID 24502291, 2014). "Rag KO recipients of CD8+ T cells from VDR KO mice had more IFN-γ and IL-17A in the SI and colon that corresponded to the increased severity of naïve CD4+ T cell induced colitis." (PMID 24502291, 2014). "The rapidly proliferating naïve donor VDR KO CD8+ T cells found residence in the MLN first and then in the IEL of the Rag KO mice where they out-competed the CD4+ T cells and contributed to colitis development by inducing IL-17A and IFN-γ production." (PMID 24502291, 2014). "VDR KO CD4+ T cells express more IL-17, and IFN-γ, proliferate more rapidly in a mixed lymphocyte reaction and induce more severe colitis than WT CD4 cells." (PMID 24502291, 2014). "Recent findings revealed that SBAs are dedicated to the remission of murine colitis, as 12-ketolithocholic acid could inhibit the secretion of IL-17A by type 3 innate lymphoid cells (ILC3) through upregulating Vitamin D receptor (VDR)." (PMID 40612235, 2025). "In DSS-induced colitis, CA, CDCA, and LCA regulated RORγt+ Treg levels via VDR, and UDCA, isoalloLCA, and 3-oxoLCA increased the proportion of ILC3s in the intestine, thereby improving epithelial barrier integrity and alleviating colitis." (PMID 39767816, 2024). "The pathophysiological significance of VDR was demonstrated in an experiment where mice lacking VDR were more vulnerable to dextran sulfate-induced colitis." (PMID 35684337, 2022). "Among the experimental colitis models, transgenic mice expressing hVDR have less colonic inflammation than mice lacking VDR." (PMID 36014889, 2022). "The epithelial integrity is maintained by vitamin D/VDR signaling, also, through other mechanisms and provides a protecting effect against TNBS-induced colitis in mice, through inhibition of myosin light chain kinase (MLCK)-induced disruption of tight junctions." (PMID 35057450, 2022). "We used VDR-KO mice to further investigate if the absence of VDR abolishes the effect of hypoxia on acute colitis." (PMID 35711312, 2022). "In addition, down-regulation of colon VDR is observed in chronic CD patients and also in mice with chronic DSS-induced colitis and fibrosis." (PMID 34579023, 2021). "Meanwhile, mice with Paneth cells VDR knockout showed a reduction in the relative abundance of beneficial bacteria (e.g., Lactobacillus) in the gut microbiota and AMPs release, while were more prone to Salmonella infection and DSS-induced colitis." (PMID 33396382, 2020).
colitis (continued). "Colitis decreases cell proliferation and increases apoptosis; a lack of VDR in several mice studies was shown to affect cell proliferation and apoptosis." (PMID 32422882, 2020). "Mice lacking the vitamin D receptor (VDR) exhibited an inflammatory phenotype with increased mucosal permeability, and were found to be susceptible to mucosal damage and colitis." (PMID 33212919, 2020). "Studies on IL-10 knockout mice have shown that concurrent vitamin D receptor (VDR) knockout leads to severe and accelerated IBD, whereas administration of exogenous vitamin D or a VDR agonist in IBD mouse models reduces tumor necrosis factor (TNF)-α and suppresses colitis." (PMID 31352652, 2019). "VDR also plays protective roles in colitis by regulating the intestinal microbiota; the absence of intestinal epithelial VDR leads to defective autophagy and affects microbial assemblage." (PMID 30804707, 2019). "By augmenting the VDR function in invariant NKT cells using VD supplementation, IL-4 and IL-13 secretion could be up-regulated and therefore aggravate Th2-mediated colitis." (PMID 27620138, 2016). "Increased colitis in Rag KO recipients of VDR KO CD8+ T cells is not a result of a difference in the CD28+/− subpopulations." (PMID 24502291, 2014). "Therefore, LCA can exert an inhibitory effect on DSS-induced colitis via VDR without inducing hypercalcemia or hepatotoxicity." (PMID 36834927, 2023). "Liu and colleagues demonstrated that VDR expression is reduced in patients with Crohn’s disease or ulcerative colitis and epithelial VDR signaling could inhibit colitis in a murine model independent of non-epithelial immune VDR actions." (PMID 36341397, 2022). "However, in VDR gene knockout (KO)colitis mice, hypoxia treatment showed no protective effect, suggesting the VDR dependency of this effect." (PMID 35711312, 2022). "The absence of the vitamin D receptor (VDR) in VDR-knockout mice resulted in gut microbiota dysbiosis compared to the wild-type mice and treatment with vitamin D in a different study ameliorated inflammatory lesions and symptoms in mouse models of colitis." (PMID 31783602, 2019). "In VDR KO mice the CD8+ T cells with a naïve phenotype were over-represented but their proliferation must have been controlled since VDR KO mice did not develop overt colitis symptoms." (PMID 24502291, 2014). "Then, using mice with deficient vitamin D receptor (VDR) in colonic epithelial cells (CEC-VDRKO) or non-intestinal epithelial cells (NEC-VDRKO), the study found that activation of vitamin D receptor can reduce the symptoms and inflammation of colitis and promote the repair of intestinal tissue." (PMID 40599770, 2025). "In addition, murine models with the transgenic expression of human VDR were protected from DSS colitis and had a reduced IEC apoptosis; therefore, VDR may also be involved in the regulation of IEC homeostasis and the maintenance of intestinal mucosal barrier integrity." (PMID 35807844, 2022). "However, the role of vitamin D and VDR in oxazolone-induced colitis had not been fully elucidated." (PMID 32541827, 2020). "The increased levels of KC and MIP-1α in the colons of VDR KO suggest that in the absence of the VDR many more inflammatory cells may be recruited to the site of injury and then produce inflammatory cytokines that result in severe and fatal form of colitis." (PMID 17397543, 2007). "However, others found lower VDR levels in patients with CD or IBD, but confirmed that colitis is enhanced in the absence of the intestinal VDR and tapered down when the intestinal VDR is overexpressed." (PMID 30321335, 2019). "VDR KO mice, in fact, did not respond to probiotics such as Lactobacillus rhamnosus strain GG (LGG) and Lactobacillus plantarum (LP) and had worse severity of Salmonella-induced colitis compared to littermates." (PMID 29112157, 2017). "VDR KO CD8+ T cells, but not WT CD8+ T cells, induced colitis in Rag KO recipients." (PMID 24502291, 2014).
colitis (continued). "Previously, we proved that hypoxia can alleviate colitis and intestinal mucosal barrier damage in DSS mice; however, after VDR knockout, hypoxia treatment could not reduce the rate of weight loss, improve the colon length, and improve the pathological score in VDR-KO colitis mice." (PMID 35711312, 2022).